GAPDH (glyceraldehyde-3-phosphate dehydrogenase)
Diseases named in the same sentence as GAPDH in open-access papers (continued):
Sharing a sentence is not in itself a finding about the gene and the disease.
E. coli infection (3 papers, 2019 to 2023). "Together, our findings suggest that DRAM1 induced by ELF1 could upregulate autophagy to resist bacterial infection and promote glycolysis (presumably through its association with GAPDH) for autophagic energy supply during E. coli infection." (PMID 37919720, 2023). "Interestingly, the DEGs encoding the T3SS needle filament protein VscF (Vp_N10_18_0060) and glyceraldehyde-3-phosphate dehydrogenase (gapA, Vp_N10_18_3876) in pathogenic E. coli infection were significantly up-regulated by 5.836- and 2.086-fold, respectively (p < 0.05)." (PMID 36496584, 2022).
endometrial cancer (3 papers, 2010 to 2025). Primary or metastatic malignant neoplasm involving the endometrium (mucous membrane that lines the endometrial cavity). "However, recent research has indicated that GAPDH, along with ACTB and 18S rRNA, may not exhibit stable expression in endometrial cancer." (PMID 41008854, 2025).
endothelial dysfunction (3 papers, 2022 to 2025). In vascular diseases, endothelial dysfunction is a systemic pathological state of the endothelium (the inner lining of blood vessels) and can be broadly defined as an imbalance between vasodilating and vasoconstricting substances produced by (or acting on) the endothelium. "One key mechanism contributing to endothelial dysfunction upon GAPDH inhibition by heptelidic acid is the decrease in NADH production." (PMID 40158853, 2025). "Another mechanism contributing to endothelial dysfunction upon GAPDH inhibition by heptelidic acid is the reduction of 1,3-BPG, a critical intermediate in glycolysis involved in actin polymerization and cell motility." (PMID 40158853, 2025). "An increased concentration of urea leads to endothelial dysfunction by promoting free radical production, inhibiting glyceraldehyde-3-phosphate dehydrogenase (GAPDH) and upregulating protein kinase C isoform activity, which negatively impacts the gut endothelial lining." (PMID 36287917, 2022).
esophageal cancer (3 papers, 2014 to 2022). A primary or metastatic malignant neoplasm involving the esophagus. "Considering the fundamental role of autophagy in tumorigenesis and the high expression levels of FOXO3, MYD88 and GAPDH in esophageal cancer, further studies are needed to evaluate the roles of these genes and autophagy in the development of esophageal cancer." (PMID 24527027, 2014). "In this study, suppression subtractive hybridization was used to identify the overexpressed genes, FOXO3, MYD88, and GAPDH, which have potential roles in the induction of autophagy in esophageal cancer cells." (PMID 24527027, 2014). "In conclusion, using the SSH method, our study revealed for the first time that the FOXO3, MYD88, and GAPDH genes are overexpressed in esophageal cancer." (PMID 24527027, 2014). "The upregulation of FOXO3, GAPDH, and MYD88 variants in esophageal cancer suggests a role for autophagy and provides new insight into the biology of esophageal cancer." (PMID 24527027, 2014). "The overexpression of the FOXO3, MYD88, and GAPDH genes could lead to the induction of autophagy genes in esophageal cancer." (PMID 24527027, 2014). "Nutrient deprivation, hypoxia, and high levels of cell division demand additional energy resources, and GAPDH overexpression could alleviate these demands by inducing both glycolysis and autophagy in esophageal cancer cells." (PMID 24527027, 2014). "Because of intraepithelial neoplasia importance in tumorigenesis of esophageal cancer, occurrence of autophagy and expression of FOXO3, MYD88, and GAPDH genes should be studied in this stage." (PMID 24527027, 2014). "Because this is the first report of the overexpression of the FOXO3, GAPDH, and MYD88 genes in esophageal cancer cells, the precise role of these genes in esophageal cancer remains to be elucidated." (PMID 24527027, 2014). "We propose that FOXO3, GAPDH, and MYD88 are novel targets for combating autophagy in esophageal cancer." (PMID 24527027, 2014).
fatty liver disease (3 papers, 2021 to 2026). A reversible condition wherein large vacuoles of triglyceride fat accumulate in liver cells via the process of steatosis. "Additionally, the internal reference protein GAPDH may be unstable in liver steatosis models; subsequent research will employ more stable housekeeping proteins to enhance reliability." (PMID 41596713, 2026). "The top predictive proteins for hepatic steatosis included TNC, GAPDH, CA2, and C9, underscoring the role of inflammatory mediators and lipid-handling proteins in this condition." (PMID 40981199, 2025).
hepatitis C virus infection (3 papers, 2020 to 2022). A viral infection caused by the hepatitis C virus. "More specifically, there is evidence demonstrating that genes often used for data normalization (i.e., β-actin, GAPDH, and 18S rRNA) display variable expression levels in the models of hepatitis C virus infections." (PMID 32089674, 2020).
Hypertension (3 papers, 2012 to 2022). The presence of chronic increased pressure in the systemic arterial system. "The relative expression levels of 7 hypertension-related differentially expressed genes shown by qPCR were analyzed and calculated according to the relative expression quantity 2−ΔCT formula, where ΔCT = CT value of target gene–CT value of the internal reference gene (GAPDH)." (PMID 35205232, 2022).
insulinoma (3 papers, 2005 to 2022). "Semiquantitative analysis comparing the OD of the SUR1 band with the OD of GAPDH band (the reference gene) from each insulinoma confirmed that SUR1 expression varied." (PMID 16266437, 2005). "In rat insulinoma INS-1 cells, GAPDH primarily showed cytoplasm localization." (PMID 36329701, 2022).
ischemic heart disease (3 papers, 2010 to 2022). "We used GAPDH as a reference gene, one of the most stable housekeeping genes in ischemic heart disease." (PMID 35837272, 2022).
lung squamous cell carcinoma (3 papers, 2021 to 2023). "In vitro, GAPDH knockdown by siRNA can significantly reduce the proliferation, migration, and invasion of lung squamous cell carcinoma cells." (PMID 34858181, 2021). "CAT, ENO1, NQO1, P4HB, and PDIA6 were unique to LUAD, while CAV1, GAPDH, GPX2, GPX3, and PDIA4 exhibited consistent trends in differential expression in both LUAD and lung squamous cell cancer, significant prognostic survival prediction (p<0.05), and excellent classification effectiveness." (PMID 37955007, 2023).
male infertility (3 papers, 2010 to 2022). The inability of the male to effect fertilization of an ovum after a specified period of unprotected intercourse. "GAPDH is particularly important in the testis for spermatogenesis and decreased sperm motility caused by male infertility." (PMID 36034828, 2022). "The destruction of the barrier that provides testes immune privilege can lead to penetration of autoimmune anti-GAPDH antibodies into the testes tissue and cause male infertility." (PMID 32370188, 2020). "Additionally, a distinct, sperm-specific form of GAPDH is isolated, the main function of which is glycolysis, and impaired functioning may cause male infertility." (PMID 32370188, 2020). "As one of the chlorinated antifertility compounds, alpha-chlorohydrin (ACH) can inhibit glyceraldehyde-3-phosphate dehydrogenase (G3PDH) activity in epididymal sperm and affect sperm energy metabolism, maturation and fertilization, eventually leading to male infertility." (PMID 20409345, 2010).
mastitis (3 papers, 2021 to 2023). Inflammation of breast tissue during lactation or postpartum due to an obstructed duct or infection. "GAPDH induces immune responses against Streptococcus dysgalactiae, S. uberis, and Staphylococcus aureus during mastitis in dairy cows." (PMID 34451993, 2021). "When mastitis developed (T1/C1), GPI, TPI1, GAPDH, PGK1, PGAM1, ENO1, and PKM in the glycolysis/gluconeogenesis pathway were upregulated, which promoted pyruvate synthesis with large amounts of ATP production." (PMID 36335251, 2022).
memory impairment (3 papers, 2022 to 2023). "This study provides a new explanation for inflammation-induced memory impairment: IL-1β through the S-sulfhydration of GAPDH by H2S leads to the combination of GAPDH and Siah and increases the stability of Siah." (PMID 37492730, 2023). "Using a rat weight drop model of TBI, we found that the combined use of both drugs prevented memory impairment and motor deficits, as well as a reduction of neurons and accumulation of GAPDH aggregates in brain tissue." (PMID 36678636, 2022).
metabolic syndrome (3 papers, 2014 to 2023). A cluster of metabolic risk factors for CARDIOVASCULAR DISEASES and TYPE 2 DIABETES MELLITUS. "Dysregulated GAPDH expression has been associated with cancer, neurodegenerative diseases, metabolic syndrome, and inflammation." (PMID 32602849, 2020).
myocardial ischemia (3 papers, 2012 to 2021). A disorder of cardiac function caused by insufficient blood flow to the muscle tissue of the heart. "Phosphorylation of Thr246 (T246) induced by protein kinase C δ under the stress of cardiac ischemia and reperfusion increases the association of GAPDH with mitochondria and inhibits GAPDH-triggered mitophagy." (PMID 31324208, 2019). "Our study found SMI attenuated the upregulation of serum GAPDH and M0R5J4 (uncharacterized protein) in ISO-induced myocardial ischemia rats, which should reflect SMI’s overall regulation on these biomarkers." (PMID 33995093, 2021). "Among them, four glycolytic enzymes, L-LDH, GAPDH, GPI, PGAM2, and two targets of MMP, gelsolin and isoform 8 of titin, are significantly released into the effluent during myocardial ischemia." (PMID 22443514, 2012).
osteoarthritis (3 papers, 2007 to 2023). A noninflammatory degenerative joint disease occurring chiefly in older persons, characterized by degeneration of the articular cartilage, hypertrophy of bone at the margins and changes in the synovial membrane. "Four target genes (LMNA, MSN, PDCD6IP, and GAPDH) with five miRNAs (hsa-let-7a-5p, hsa-let-7b-5p, hsa-mir-15a-5p, hsa-mir-26a-5p, and hsa-mir-23b-3p) were associated with the pathway in osteoarthritis according to the results of the miRNet network analysis." (PMID 38132172, 2023). "It is worthwhile to mention that recent research on healthy (porcine) AC identified GAPDH as one of the most stably expressed genes, whereas it is considered a less stable reference gene in full osteoarthritis (human) patients older than 60 years." (PMID 29793458, 2018). "The most frequently used rat model for analyzing properties of drugs on the pathology of osteoarthritis is the injection of the metabolic inhibitor monosodium iodoacetate into the joint, which inhibits the activity of glyceraldehyde-3-phosphate dehydrogenase in chondrocytes." (PMID 17284318, 2007).
Peri-Implantitis (3 papers, 2016 to 2023). An inflammatory process with loss of supporting bone in the tissues surrounding functioning DENTAL IMPLANTS. "Four out of nine RNA-enriched genes specific to peri-implantitis were plasmin receptor/glyceraldehyde-3-phosphate dehydrogenase (GAPDH) (plr/gapA) genes." (PMID 33425781, 2020). "Moreover, the activity of plasmin receptor/glyceraldehyde-3-phosphate dehydrogenase genes was higher in peri-implantitis." (PMID 33425781, 2020).
retinal diseases (3 papers, 2017 to 2025). "Glyceraldehyde-3-phosphate dehydrogenase (GAPDH) is a glycolytic enzyme and is also involved in regulating cell death, its role in the development of retinal diseases has been explored in previous studies." (PMID 36836125, 2023).
sleep disorder (3 papers, 2022 to 2025). A change from the patient's baseline sleeping pattern, in the hours slept and/or an alteration/dysfunction in the stages of sleep. "ATP5B, COX5A, GAPDH NDUFV2, SOD1, UQCRC1, and UQCRC2 have been reported as sleep deprivation and sleep disorder-related genes, and these studies have contributed to the development of candidate biomarkers for the diagnosis and treatment of plateau-induced sleep disorders." (PMID 36860517, 2023).
sleeping sickness (3 papers, 2013 to 2022). "Topology analysis of the miRNA-gene network revealed three genes (RPS27A, UBA52 and GAPDH) involved in the regulation of critical pathways related to the development of African trypanosomiasis." (PMID 36354791, 2022).
small cell lung carcinoma (3 papers, 2017 to 2024). Small cell lung cancer (SCLC) is a highly aggressive malignant neoplasm, accounting for 10-15% of lung cancer cases, characterized byrapid growth, and early metastasis. "MA treatment of small cell lung carcinoma DMS114 cells caused downregulation of glycolytic proteins (ALDOA, GAPDH, ENO1, PyKM2 and LDHA) as well as upregulation of OxPhos proteins (cytochrome b-c1 complex subunit 2 and cytochrome c oxidase subunit 5B)." (PMID 39288141, 2024).
T cell lymphoma (3 papers, 2014 to 2022). "The antiproliferative properties of these extracts on the human T-cell lymphoma cell line, HuT 78, were observed and related to histone hyperacetylation and downregulation of GAPDH expression." (PMID 25608858, 2015).
thyroid tumour (3 papers, 2000 to 2022). "Raw fluorescence data were normalized with respect to the GAPDH expression level in all samples and the CLU transcript variants expression obtained in thyroid tumour samples was normalized to the corresponding normal samples." (PMID 25934174, 2015).
vitiligo (3 papers, 2012 to 2014). Generalized well circumscribed patches of leukoderma that are generally distributed over symmetric body locations and is due to autoimmune destruction of melanocytes. "The IL1B transcript levels were compared in 95 vitiligo patients and 105 age matched unaffected controls after normalization with GAPDH transcript levels." (PMID 25221996, 2014). "Comparison of the findings showed significant increase in expression of TNFB mRNA in 166 vitiligo patients compared to 175 unaffected controls after normalization with GAPDH expression as suggested by mean ΔCp values (p = 0.001)." (PMID 24312346, 2013). "Comparison of the findings showed significant increase in expression of ICAM1 mRNA in 166 vitiligo patients than in 175 unaffected controls after normalization with GAPDH expression as suggested by mean ΔCp values (p = 0.008)." (PMID 24312346, 2013). "Comparison of the findings showed significantly increased expression of TNF-α transcripts in 157 vitiligo patients than in 174 unaffected controls after normalization with GAPDH expression as suggested by mean ΔCp values (p = 0.0005)." (PMID 23284977, 2012).
ZIKV infection (3 papers, 2018 to 2021). "There was a trend towards increase in spliced XBP1/GAPDH in palmitate treated cells compared to ZIKV infection alone." (PMID 34200091, 2021). "Our results indicate that both isoforms are upregulated during ZIKV infection of prostate cells, as compared to GAPDH expression and uninfected cell controls." (PMID 33378361, 2020). "The ratio of LC3-II/GAPDH in each group was significantly increased at different times after ZIKV infection at different MOIs, indicating that the production of lipidated LC3-II increased." (PMID 29762492, 2018).
acute lymphoblastic leukemia (2 papers, 2011 to 2015). Leukemia with an acute onset, characterized by the presence of lymphoblasts in the bone marrow and the peripheral blood. "We observed that HNE-modified GAPDH was also degraded in an extract of HL-60 cells, another human myeloblastic leukemia cell line, but not in an extract of Jurkat cells, a lymphoblastic leukemia cell line (data not shown)." (PMID 21904640, 2011). "In acute lymphoblastic leukemia (ALL), levels of HIF-1α, GLUT1, GLUT3, CA4, and glyceraldehyde-3-phosphate dehydrogenase (GAPDH) were significantly greater in leukemic cells compared to healthy blood cells." (PMID 26437434, 2015).
acute myelocytic leukemia (2 papers, 2012 to 2025). "In the acute myelocytic leukemia cell line KG-1, MDR1 expression level was the highest (64 copies/103 GAPDH), followed by those of MRP4 (23 copies/103 GAPDH) and MRP1 (15 copies/103 GAPDH)." (PMID 23181130, 2012).
allergic asthma (2 papers, 2022 to 2024). A asthma with a basis in a pathological type I hypersensitivity reaction. "To our knowledge, we are the first to confirm that probiotic and pathogenic GAPDH may share similar functions in adhering to host plasminogen, but they have distinct immunomodulatory activities in allergic asthma depending on their respective dehydrogenase activities." (PMID 36175886, 2022). "GAPDH reverses the activation of Th2 cells induced by M2 through its glycolytic activity, which plays an important immunomodulatory role in preventing allergic asthma." (PMID 39268462, 2024).
allergic disease (2 papers, 2022 to 2024). An immune response that occurs following re-exposure to an innocuous antigen, and that requires the presence of existing antibodies against that antigen. "Although few reports have suggested that probiotic secreted GAPDH is an immunomodulator, the anti-inflammatory effects of probiotics in allergic disease are well reported." (PMID 36175886, 2022). "Therefore, it is rational to propose that probiotics may interact with host plasminogen through GAPDH to induce immunoregulatory effects in allergic diseases." (PMID 36175886, 2022).
amyotrophic lateral sclerosis (2 papers, 2013 to 2022). Amyotrophic lateral sclerosis (ALS) is a neurodegenerative disease characterized by progressive muscular paralysis reflecting degeneration of motor neurons in the primary motor cortex, corticospinal tracts, brainstem and spinal cord. "One of the aims of our study was todetermine whether GAPDH and tTG can not only participate in the aggregation ofmutant huntingtin, but also contribute to the pathogenesis of a completelydifferent disease, amyotrophic lateral sclerosis (ALS)." (PMID 23819039, 2013). "Similarly, theblockage of GAPDH synthesis was found for the first time to reduce the degreeof aggregation of mutant superoxide dismutase 1 (G93A) in a model ofamyotrophic lateral sclerosis (ALS)." (PMID 23819039, 2013).
Anxiety (2 papers, 2024). Intense feelings of nervousness, tension, or panic often arise in response to interpersonal stresses. "In Citrus reticulata, GAPDH exhibits the greatest expression security under drought anxiety, whereas ACT is the most steady under low-temperature anxiety." (PMID 39336816, 2024). "A research study examining the option of reference genetics for RT-qPCR in Zea mays under hormone treatment conditions recognized EF1-α, TUB, and GAPDH as the most appropriate recommendation genes under ABA hormonal agent stress and anxiety treatment." (PMID 39336816, 2024). "In a similar way, in Lycopersicon esculentum under abiotic stress and anxiety, EF1-α maintains stable expression under low-temperature problems, unlike GAPDH, which shows bad stability." (PMID 39336816, 2024).
autism (2 papers, 2012 to 2016). Persistent deficits in social interaction and communication and interaction as well as a markedly restricted repertoire of activity and interest as well as repetitive patterns of behavior. "Based on our analysis of gene expression stability using geNorm and NormFinder algorithms in parallel, GAPDH was determined as the most stable HKG to be used as an internal control for salivary transcriptome analysis and/or validation of microarray results by RT-qPCR in male childhood autism." (PMID 27754318, 2016).
autoimmune retinopathies (2 papers, 2017 to 2023). "Interestingly, autoantibodies against GAPDH in patients with autoimmune retinopathy were associated with disease severity." (PMID 36836125, 2023).
bipolar disorder (2 papers, 2010 to 2024). A disorder of the brain that causes unusual shifts in mood, energy, activity levels and the ability to carry out day-to-day tasks. "ENO1, PFKP, and GAPDH were also downregulated in bipolar disorder with a similar magnitude of expression change in both states." (PMID 39125835, 2024). "GAPDH showed similar mRNA levels in the samples from controls to those in the bipolar disorder samples (P = 0.12)." (PMID 20195522, 2010).